AMH (anti-Mullerian hormone)
Diseases named in the same sentence as AMH in open-access papers (continued):
Sharing a sentence is not in itself a finding about the gene and the disease.
childhood cancer (4 papers, 2014 to 2025). "Although AMH has been certified as a valid marker for ovarian reserves, it is not still used as gold standard in follow-up programs for female childhood cancer survivors (CCS)." (PMID 34944951, 2021). "Some studies suggest that AMH may be a useful marker of ovarian follicular reserve in survivors of childhood cancer and/or HSCT." (PMID 40074785, 2025).
dermoid cyst (4 papers, 2015 to 2022). A tumor consisting of displaced ectodermal structures along the lines of embryonic fusion, the wall being formed of epithelium-lined connective tissue, including skin appendages, and containing keratin, sebum, and hair. "In the present study, we found significant decreases in the postoperative AFC and serum AMH levels of the ovary operated for dermoid cysts." (PMID 32341825, 2020). "In our study, we also found lower serum AMH values in patients with endometrioma than in patients with dermoid cysts before surgery." (PMID 32341825, 2020). "They found a decrease in AMH levels from 3.0 ng/mL to 2.5 ng/mL in patients with dermoid cysts and a decrease from 2.0 ng/mL to 0.8 ng/mL in patients with endometrioma." (PMID 32341825, 2020). "Additionally, the present study outcomes showed that the mean decrease in serum AMH level among participants with endometrioma was significantly higher than the “serous cystadenoma”, “dermoid cyst”, and “other” groups." (PMID 36120464, 2022). "Similarly, in patients with unilateral ovarian endometrioma, the decrease in AMH levels was more significant and lasted longer compared to women who underwent surgery for dermoid cysts." (PMID 26596960, 2015). "In our study, we found a significantly higher decrease in serum AMH levels and operated side AFC levels after surgery in patients with endometrioma than in patients with dermoid cysts." (PMID 32341825, 2020). "We detected that the preoperative and postoperative AMH and AFC levels in patients with endometrioma were lower than those in patients with dermoid cysts." (PMID 32341825, 2020). "Laparoscopic stripping has destructive effects on serum AMH levels and the operated side AFC levels after surgery for patients with endometrioma and dermoid cysts, and laparoscopic excision of endometrioma has more destructive effects on ovarian reserve than dermoid cysts." (PMID 32341825, 2020). "In addition, the decrease rate in AMH and AFC levels was higher in patients with endometrioma than in those with dermoid cysts." (PMID 32341825, 2020).
lung carcinoma (4 papers, 2013 to 2024). "Furthermore, 5%–8% of NSCLCs exhibit high AMHR2 expression, suggesting that AMH may inhibit the progression of some lung cancers." (PMID 39230026, 2024). "Anti-Mullerian hormone (AMH), a member of the transforming growth factor/bone morphogenetic protein superfamily, participates in regulating epithelial-mesenchymal transition (EMT), epithelial plasticity, and chemoresistance in lung cancer." (PMID 35676660, 2022).
osteoporosis (4 papers, 2020 to 2026). A condition of reduced bone mass, with decreased cortical thickness and a decrease in the number and size of the trabeculae of cancellous bone (but normal chemical composition), resulting in increased fracture incidence. "An early decrease in sex hormone levels resulting from reduced AMH in hysterectomized patients may cause earlier bone loss and increase the risk of osteoporosis as compared to patients with an intact uterus." (PMID 37972094, 2023). "In our study, we found hysterectomy itself could be associated with an increased risk of osteoporosis and fracture might related to a decreased AMH." (PMID 33259542, 2020).
Ovarian Hyperandrogenism (4 papers, 2015 to 2023). Increased production of androgens by the ovaries. "AMH levels are associated with elevated androgen levels and have been proposed as a diagnostic marker for ovarian hyperandrogenism, but the role of AMH in the diagnosis of PCOS is uncertain." (PMID 26566413, 2015). "Whether these mostly missense variants in AMH and AMHR2 induce the elevated circulating and intrafollicular levels of AMH and the ovarian hyperandrogenism of PCOS women remains unclear." (PMID 35012577, 2022). "Both AMH and AMHR2 gene variants regulate intra-ovarian follicle development and hypothalamic GnRH function, and possibly ovarian androgen production, and may underlie elevated circulating AMH levels and ovarian hyperandrogenism in PCOS women." (PMID 37834765, 2023).
Sertoli cell tumor (4 papers, 2016 to 2022). A sex cord-stromal tumor of the testis or the ovary. "Serum AMH serves also as a potential biomarker in the diagnosis of Sertoli cell tumor as a result of the increased AMH production from neoplastic Sertoli cells." (PMID 35158647, 2022). "However, the re-expression of the AMH has been reported to occur in patients with Sertoli cell-only syndrome and Sertoli cell tumors." (PMID 35158595, 2022).
benign ovarian tumors (3 papers, 2014 to 2023). "The decline rates of serum AMH levels after cystectomy for benign ovarian tumors have been reported to be lower than those observed after cystectomy for endometriomas." (PMID 25510324, 2014). "The effects of cystectomy for benign ovarian tumors on AMH levels have been assessed in a few studies." (PMID 25510324, 2014).
central obesity (3 papers, 2023 to 2024). "WHR also showed a negative association with AMH, suggesting that abdominal obesity may adversely impact ovarian reserve." (PMID 39683543, 2024). "The relationship between BMI and AMH has been explored in various studies, the majority of them suggesting an inverse relationship between BMI and AMH levels, especially in PCOS and central obesity patients." (PMID 39336427, 2024). "Factors including maternal age, BMI, AMH, menstrual cycle, IR, elevation of FPG, elevation of blood pressure, central obesity, and phenotypes of PCOS were stratified and effects of LS on LBR were analyzed in the subgroup analysis." (PMID 37891650, 2023).
Crohn disease (3 papers, 2016 to 2020). A gastrointestinal disorder characterized by chronic inflammation involving all layers of the intestinal wall, noncaseating granulomas affecting the intestinal wall and regional lymph nodes, and transmural fibrosis. "Further, lower AMH levels were also found in women with Crohn’s disease, with polymyositis, and in those with juvenile idiopathic arthritis as compared to healthy controls." (PMID 31511566, 2019). "Patients with Crohn’s disease or dermatomyositis had decreased anti-Müllerian hormone (AMH) and antral follicle count (AFC), which suggested that inflammation adversely affect ovarian reserve." (PMID 27272680, 2016).
Endometrial Cyst (3 papers, 2015 to 2022). It is caused by endometriosis, and formed when a tiny patch of endometrial tissue (the mucous membrane that makes up the inner layer of the uterine wall) bleeds, sloughs off, becomes transplanted, and grows and enlarges inside the ovaries. "It reports that the initial AMH level is lower in patients with endometrial cysts." (PMID 36676638, 2022).
Impaired glucose tolerance (3 papers, 2022 to 2024). An abnormal resistance to glucose, i.e., a reduction in the ability to maintain glucose levels in the blood stream within normal limits following oral or intravenous administration of glucose. "However, after trehalose treatment, the T, INS, E2, AMH, and HOMA-IR levels decreased, and the impaired glucose tolerance was also repaired (P < 0.01)." (PMID 38195648, 2024).
Klinefelter syndrome (3 papers, 2016 to 2024). A sex chromosome disorder caused by the presence of an extra X chromosome in the male karyotype. "At the onset of puberty, like in normal boys, androgens provoke a physiological decrease in serum AMH also in patients with Klinefelter syndrome." (PMID 27799946, 2016). "In syndromic disorders, assessment of serum AMH has shown that Sertoli cell function is preserved in boys with Klinefelter syndrome until mid-puberty, while it is affected in patients with Noonan, Prader-Willi or Down syndromes." (PMID 38501100, 2024). "In patients with Klinefelter syndrome, serum AMH, as well as other reproductive hormones, are within the normal range in infants and children, indicating that endocrine testis function is not affected before puberty." (PMID 38501100, 2024).
ovarian disorder (3 papers, 2019 to 2026). A disease involving the ovary. "The peripheral AMH level has become representative of the ovarian reserve pool and is currently a promising marker for fertility and a diagnostic marker for ovarian disorders in domestic animals." (PMID 31817280, 2019). "In female hosts, FMT resulted in a marked reduction in NAM concentration in the blood, and ovarian disorders-including weight reduction, reduced follicle number (mainly PmF), and altered folliculogenesis dynamics-associated with the decrease in AMH, GDF9, BMP15, and MVH proteins." (PMID 38948060, 2024). "Anti-Müllerian hormone (AMH) is a dimeric glycoprotein secreted from the granulosa cells (GCs), which is widely used as a diagnostic tool in different ovarian disorders." (PMID 41515619, 2026). "Background and Clinical Significance: Anti-Müllerian hormone (AMH) is a dimeric glycoprotein secreted from the granulosa cells of the preantral and small antral follicles, which has entered routine clinical practice as a valuable tool for the diagnosis of different ovarian disorders." (PMID 41515619, 2026).
Peutz-Jeghers syndrome (3 papers, 2016 to 2022). An autosomal dominant disorder caused by pathogenic variants in the STK11 gene, characterized by hamartomatous polyps in the gastrointestinal tract, mucocutaneous pigmentation and increased risk of GI and extra-GI malignancies. "However, AMH is also elevated in boys with Peutz-Jeghers syndrome, in whom Sertoli cell proliferations produce high estrogen levels leading to suppressed FSH." (PMID 35712256, 2022). "Altogether, these observations raise the possibility that the hyperoestrogenism observed in CAIS and Peutz-Jeghers syndrome may account for the elevation in testicular AMH production." (PMID 32934281, 2020). "However, other conditions like Peutz-Jeghers syndrome (PJS), characterised by low FSH, also have increased AMH." (PMID 32934281, 2020).
precocious puberty (3 papers, 2016 to 2023). Unusually early sexual maturity. "Knowledge of the potential associations between INHB, AMH and precocious puberty has public health significance for the diagnosis of precocious puberty in girls." (PMID 37996919, 2023). "We included observational clinical studies reporting the serum levels INHB and AMH in girls with precocious puberty." (PMID 37996919, 2023). "The androgen-dependent inhibition of AMH has also been observed in central precocious puberty and in male-limited gonadotropin-independent precocious puberty (testotoxicosis), clearly indicating that androgens are responsible for AMH down-regulation independently of gonadotropin levels." (PMID 27799946, 2016).
preeclampsia (3 papers, 2017 to 2023). Preeclampsia is a hypertensive disorder of pregnancy that is characterized by new-onset hypertension with proteinuria presenting after 20 weeks of gestation, and depending on mild or severe forms may initially present with severe headache, visual disturbances, and hyperreflexia. "Our systematic review suggests that higher AMH levels are suggestive of a lower risk of developing preeclampsia during the pregnancy course." (PMID 30288163, 2017). "One study reported that women with and AMH value below the 10th percentile of the studied population had a 3.3 increased risk of developing preeclampsia (OR 3.3, 95% CI 1.2–8.7, p = 0.01)." (PMID 30288163, 2017). "Current evidence suggests that higher levels of serum AMH are suggestive of a lower risk of developing preeclampsia." (PMID 30288163, 2017). "The purpose of the present systematic review is to investigate whether serum AMH levels significantly differ among women that are at risk of developing preeclampsia." (PMID 30288163, 2017). "Limitations of our study: Our study is the first systematic review in the literature which evaluated the utility of AMH as a predictive factor of preeclampsia." (PMID 30288163, 2017). "Current data are suggestive of the potential predictive value of serum AMH as its levels seem to be lower among women that develop preeclampsia." (PMID 30288163, 2017). "Nevertheless, the potential prognostic value of AMH for the detection of preeclampsia is also supported by studies that suggest that preeclampsia itself can significantly alter ovarian reserve status and function and thus, decrease AMH levels." (PMID 30288163, 2017). "AMH is also elevated in women with PCOS, which predisposes gestational hypertension, among other adverse outcomes." (PMID 30288163, 2017). "Our study demonstrated that high AMH levels increased the risk of PIH and GDM in multiple deliveries after ART (Gestational hypertension: aOR2 = 2.26, 95% CI: 1.20-4.22; Gestational diabetes mellitus: aOR2 = 2.40, 95% CI: 1.48-3.91), low AMH levels increase the risk of oligohydramnios." (PMID 36896183, 2023). "We sought to determine whether there is any association between ovarian reserve, as assessed by Anti-Mullerian hormone (AMH), and preeclampsia (PE)." (PMID 31752768, 2019). "To date, it remains unknown whether the suppression of AMH is correlated with the process of placentation and whether increased levels of AMH could lead to preeclampsia." (PMID 30288163, 2017). "Thus, a defective placentation may increase AMH levels and lead to preeclampsia." (PMID 30288163, 2017).
Primary amenorrhea (3 papers, 2023 to 2025). "The clinical phenotype of primary amenorrhea with reduced ovarian reserve reflected by reduced AMH levels and hypotrophic ovaries is compatible with the known effects of BMP15 on GC proliferation and an arrest in follicle maturation." (PMID 39850788, 2025).
rheumatoid arthritis (3 papers, 2015 to 2024). A chronic, systemic autoimmune disorder characterized by inflammation in the synovial membranes and articular surfaces. "Patients with rheumatoid arthritis (RA), Behçet’s disease, and spondyloarthritis (SpA) have been found to have lower AMH levels compared to age-matched controls." (PMID 39001304, 2024). "Women with recent-onset rheumatoid arthritis (RA) had comparable AMH levels with healthy control participants, and methotrexate use did not affect AMH levels." (PMID 32770239, 2020). "Serum concentrations of the anti-Müllerian hormone (AMH) were not lower in women treated with methotrexate for rheumatoid arthritis than in controls." (PMID 26490561, 2015).
Thyroid disorders (3 papers, 2019 to 2024). "During the initial phases of the thyroid disease, the disease may cause an inflammatory process involving the ovaries that stimulates AMH production and predisposes young women to PCOS or severe PCOS phenotypes." (PMID 37635968, 2023). "In particular, the presence of thyroid antibodies in ovarian follicular fluid and their correlation with AMH serum levels were demonstrated." (PMID 37635968, 2023). "Thyroid disorders are common in women undergoing in vitro fertilization, with the majority of studies reporting an inverse relation between TSH and AMH level." (PMID 39336427, 2024).
type 1 diabetes (3 papers, 2015 to 2022). "In another cohort of 150 premenopausal women with type 1 diabetes, higher concentrations of AMH were associated with lower levels of SBP before and after adjustment for age." (PMID 30766706, 2017). "Strengths of this report include its well-phenotyped population of women with type 1 diabetes, enabling examination of AMH with CVD risk factors as well as CAC, cIMT, and renal function." (PMID 30766706, 2017). "Among women with type 1 diabetes, AMH has minimal associations with CVD risk factors apart from chronologic age, but AMH may have a non-linear relationship with CAC and associations with cIMT." (PMID 30766706, 2017). "Future investigations should also explore whether the reproductive abnormalities experienced by women with type 1 diabetes are CVD risk factors apart from ovarian markers such as AMH." (PMID 30766706, 2017). "Among women with type 1 diabetes, AMH and cIMT and between AMH and other measures of vascular flow were not related." (PMID 30766706, 2017). "Ovarian function is altered in diabetic women throughout reproductive life and in menopause, as shown by an earlier decline in AMH and inhibin B levels in type 1 diabetes." (PMID 25750666, 2015). "We examined whether AMH concentrations were associated with markers of subclinical cardiovascular disease (CVD) and kidney disease among women with type 1 diabetes." (PMID 30766706, 2017). "Participants included women with type 1 diabetes and ≥1 AMH measurement (n = 390)." (PMID 30766706, 2017). "As previous reports have noted a U-shaped relationship between AMH and CVD risk factors, our hypotheses were that extremes of AMH are associated with CVD risk factor profile and measures of subclinical atherosclerosis and renal disease among women with type 1 diabetes." (PMID 30766706, 2017).
type 2 diabetes mellitus (3 papers, 2019 to 2024). A type of diabetes mellitus that is characterized by insulin resistance or desensitization and increased blood glucose levels. "Diabetes type 2 diagnosed before cancer did not affect the expression of AMH in EC tissues (Mann–Whitney U test, AMH: Z = 0.019, p = 0.985)." (PMID 30884769, 2019).
aneuploidy (2 papers, 2021 to 2023). Chromosomal disorder consisting of the presence a chromosomal abnormality in which there is an addition or loss of chromosomes within a set. "When directly comparing the predictive values of age or AMH, AMH was a superior predictor of aneuploidy for patients < 38 years, with age being far more predictive of aneuploidy risk in patients ≥ 38 years." (PMID 36739415, 2023). "Several studies were unable to confirm any independent association of AMH, AFC, basal FSH levels and the number of previous pregnancies and spontaneous miscarriages with aneuploidy in individuals who experienced pregnancy loss, consistent with our study." (PMID 33819190, 2021).
Autoimmunity (2 papers, 2019 to 2022). The occurrence of an immune reaction against the organism's own cells or tissues. "In conclusion, in our cohort of women, age proved to be a better predictor of AMH levels than any of the other factors linked to thyroid function and autoimmunity." (PMID 35965323, 2022). "In our cohort of women, age proved to be a better predictor of AMH levels than any of the other factors linked to thyroid function and autoimmunity." (PMID 35965323, 2022). "The first lies in the relatively small number of women involved and the retrospective design, which made it impossible to assess any temporal relationship between AMH and thyroid function/autoimmunity." (PMID 35965323, 2022). "A literature search conducted at the end of 2021 identified several papers in which AMH and thyroid function and/or autoimmunity were evaluated." (PMID 35965323, 2022). "Endocrinological diagnoses in our women were heterogeneous (e.g. possible high AMH levels in PCOS patients) and factors other than thyroid function and autoimmunity may have influenced AMH levels." (PMID 35965323, 2022). "We also observed a very strong inverse correlation between age and both AMH and FSH in our women of reproductive age, independently from thyroid function and autoimmunity." (PMID 35965323, 2022). "Our objective was to study thyroid determinants (thyroid function, treatments, autoimmunity, thyroid volume) of AMH serum values in an endocrinological setting, in order to verify the hypothesis of differences in AMH levels in women with or without thyroid dysfunctions." (PMID 35965323, 2022).